ATF7IP2 (activating transcription factor 7 interacting protein 2)
Description:
Recruiter that couples transcriptional factors to general transcription apparatus and thereby modulates transcription regulation and chromatin formation. Can both act as an activator or a repressor depending on the context. Mediates MBD1-dependent transcriptional repression, probably by recruiting complexes containing SETDB1. The complex formed with MBD1 and SETDB1 represses transcription and probably couples DNA methylation and histone H3 'Lys-9' trimethylation (H3K9me3) activity (Probable).
Synonyms: MCAF2; FLJ12668
Tractability: PROTAC: ubiquitination databases record sites on it.
Gene: Protein-coding gene on chromosome 16 (10,326,434 to 10,483,640, forward strand). Ensembl gene ENSG00000166669.
Subcellular location: Nucleus
Gene Ontology:
Molecular function: transcription coregulator activity
Biological process: regulation of DNA-templated transcription
Cellular component: nucleus; transcription regulator complex
Genetic constraint (gnomAD): Loss-of-function variants: 24 observed, 37.13 expected, observed/expected ratio (o/e) 0.65, 90% interval 0.47 to 0.91. The upper end of that interval is the gene's LOEUF score, 0.91, which puts it in group 3 of 6, group 1 being the genes least tolerant of losing a copy. Missense variants: 616 observed, 558.38 expected, observed/expected ratio (o/e) 1.1, 90% interval 1.03 to 1.18. Synonymous variants: 220 observed, 195.31 expected, observed/expected ratio (o/e) 1.13, 90% interval 1.01 to 1.26.
Homologues: Orthologues: chimpanzee ATF7IP2 (98% identical), macaque ATF7IP2 (94% identical), pig ATF7IP2 (73% identical), dog ATF7IP2 (72% identical), rabbit ATF7IP2 (66% identical), rat Atf7ip2 (45% identical), mouse Atf7ip2 (44% identical), tropical clawed frog atf7ip2 (23% identical), Drosophila melanogaster wde (19% identical), zebrafish atf7ip2 (11% identical). Paralogues in human: ATF7IP (27% identical).
Diseases named in the same sentence as ATF7IP2 in open-access papers:
ATF7IP2 is named in the same sentence as 7 diseases in open-access papers, as found by Europe PMC text mining. Sharing a sentence is not in itself a finding about the gene and the disease. The quoted sentences say what the papers report.
promyelocytic leukemia (1 paper, 2017). "There is also evidence for ATF7IP2 and ATRX transcriptional activation role, through SP1 and DAXX interaction, in promyelocytic leukemia nuclear bodies." (PMID 28293299, 2017).
cancer (1 paper, 2022). A tumor composed of atypical neoplastic, often pleomorphic cells that invade other tissues. "Six genes (PDXDC1, ATF7IP2, LIN7C JTB, TTL, DVL2), which regulate the ERG signal transduction pathways, were retained in 4 out of 9 LT patients, were significantly involved in transcriptional mis-regulation in cancer (multiple testing adjusted p-value = 0.025)." (PMID 35773268, 2022).
tumor (1 paper, 2019). "Unfolded protein response, in which one of the eGenes ATF7IP2 was involved, is also reported to contribute to tumor progression and carcinogenesis." (PMID 31671645, 2019).
ATF7IP2 also shares sentences with these, for which no sentence is quoted: congenital cataracts (1 paper); neuropathy (1); retina degeneration (1); Retinal dystrophy (1).